TLR9 (toll like receptor 9)
Diseases named in the same sentence as TLR9 in open-access papers (continued):
Sharing a sentence is not in itself a finding about the gene and the disease.
common variable immunodeficiency (5 papers, 2012 to 2023). "Broad Toll-like receptor 9 (TLR9) signalling defects after CpG in vitro stimulation have been described in common variable immunodeficiency (CVID)." (PMID 22454615, 2012). "RA has been shown to normalize the proliferation of defective B cells and restore their IgG-producing capacities as well as IL-10 production in the presence of TLR9/CD180 stimulation in common variable immunodeficiency (CVID) models." (PMID 30081517, 2018). "CD21low B-cells are expanded in a subset of patients with common variable immunodeficiency (CVID) and in some other immunological disorders and are characterized by high-constitutive ERK activation, low responsiveness to TLR-9 and BCR stimuli, and propensity to apoptosis." (PMID 25657650, 2015).
encephalitis (5 papers, 2014 to 2022). An acute inflammatory process affecting the brain parenchyma. "Here, we show that EV71 engagement with intracellular receptor TLR9 elicits IL-12p40-iNOS signaling causing encephalitis in mice." (PMID 35399111, 2022). "Dual TLR2/9 ablation resulted in the highly enhanced mortality with exacerbated symptoms of encephalitis compared with TLR2 or TLR9 deficiency alone, coinciding with highly increased viral load in central nervous system tissues." (PMID 29760708, 2018). "Mice with single deficiencies of TLR7, TLR9, or TLR13 showed unaltered ability to control lung infection but were moderately more susceptible to encephalitis, in association with a decreased ability of microglia to mount cytokine responses in vitro." (PMID 32209688, 2020). "The ablation of TLR2, TLR7, and TLR9 molecules did not significantly affect the progression of encephalitis caused by JEV." (PMID 25188232, 2014). "Blocking TLR9 signaling with CpG-ODN antagonist ameliorated IL-12p40 response, brainstem inflammation, and limb paralysis in mice with EV71-induced encephalitis." (PMID 35399111, 2022). "Using this model, mice with single deletions in specific TLRs, such as TLR2, TLR7, TLR9, or TLR13 were fully capable of controlling bacterial replication in the lung, but 30 to 45% of them developed encephalitis late during infection." (PMID 32209688, 2020).
esophageal adenocarcinoma (5 papers, 2014 to 2025). A malignant tumor with glandular differentiation arising predominantly from Barrett mucosa in the lower third of the esophagus. "In esophageal epithelium, TLR9 expression increases during premalignant and malignant changes and TLR9 activation stimulates invasion in esophageal adenocarcinoma cells." (PMID 27008696, 2016).
liver cancer (5 papers, 2015 to 2026). An epithelial or non-epithelial malignant neoplasm that arises from the liver. "TLRs are upregulated in HCC tissues, and inhibition of TLR7 and TLR9 eliminates the proliferation of liver cancer cells." (PMID 33915844, 2021).
lung adenocarcinoma (5 papers, 2014 to 2024). A carcinoma that arises from the lung and is characterized by the presence of malignant glandular epithelial cells. "Activation of the TLR9 pathway in some cases can lead to the secretion of TNFa, as, for example, in the case of lung adenocarcinoma A549 cells." (PMID 38791341, 2024). "In our recent study, we demonstrated that the activation of Toll-like receptor 9 (TLR9) induced the synthesis of endogenous S1P in lung adenocarcinoma cells." (PMID 36010601, 2022). "The A549 human lung adenocarcinoma cell line highly expresses TLR9 and also exhibits positive expression of the Runt-related transcription factor 3 (Runx3)." (PMID 24748977, 2014). "Indeed, it has been demonstrated that TLR9 stimulation combined with RT treatment leads to humoral antitumor immune responses, increases tumoral infiltration, reduces pulmonary metastases, and improves the survival in mice bearing a murine lung adenocarcinoma (Lewis lung adenocarcinoma)." (PMID 31886298, 2019).
nasal polyp (5 papers, 2012 to 2025). "The study enrolled 45 patients and included an in vitro investigation using cultured dispersed nasal polyp cells (DNPCs) to assess the effects of TLR9 activation on HMGB1 and immune response." (PMID 40807013, 2025). "have analyzed by flow cytometry and Luminex naïve nasal polyp and turbinate tissues, as well as human tissues after in vivo and in vitro stimulation with a TLR9 agonist, CpG." (PMID 26061394, 2015). "On the other hand, a low TLR9 expression has been reported by Ramanatan and coworkers in chronic rhinosinusitis with nasal polyps patients, in comparison to healthy specimens." (PMID 22577387, 2012).
non-Hodgkin lymphoma (5 papers, 2012 to 2023). Distinct from Hodgkin lymphoma both morphologically and biologically, non-Hodgkin lymphoma (NHL) is characterized by the absence of Reed-Sternberg cells, can occur at any age, and usually presents as a localized or generalized lymphadenopathy associated with fever and weight loss. "RNA therapies that aim for immune stimulation are also under development and mainly focus on anti-cancer treatments such as ASO 1018 ISS targeting TLR-9 for enhancement of cytotoxic effort function in non-Hodgkin’s lymphoma." (PMID 37109050, 2023). "A phase I study of TLR9 stimulation combined with rituximab in non-Hodgkin lymphoma showed no toxicity, induction of interferon and interferon inducible genes and an overall response rate of 32% (6/19)." (PMID 25112836, 2014).
oral squamous cell carcinoma (5 papers, 2022 to 2026). "TLR9 stimulation demonstrated TLR9/AP1/cyclin D1 signaling-mediated carcinogenesis in oral squamous cell carcinomas (HB cells in vitro)." (PMID 36611945, 2022).
osteoarthritis (5 papers, 2012 to 2025). A noninflammatory degenerative joint disease occurring chiefly in older persons, characterized by degeneration of the articular cartilage, hypertrophy of bone at the margins and changes in the synovial membrane. "Besides, the therapeutic effects of curcumin in osteoarthritis are possibly exerted via modulating the miR-143/ROCK1/TLR9 and miR-124/NF-kB pathways." (PMID 36177350, 2022).
Parkinson disease (5 papers, 2016 to 2024). A progressive degenerative disorder of the central nervous system characterized by loss of dopamine producing neurons in the substantia nigra and the presence of Lewy bodies in the substantia nigra and locus coeruleus. "Here the authors show that activation of Toll-like receptor 9 controlled by microglial glucocorticoid receptor signaling, contributes to dopamine neuron loss in a model of Parkinson’s disease." (PMID 29934589, 2018). "TLR9 was significantly enriched in the pathways of Parkinson disease, ribosome, and spinocerebellar ataxia." (PMID 37128203, 2023). "TLR9 is likely involved in MPTP-triggered experimental Parkinsonism." (PMID 29934589, 2018).
peritonitis (5 papers, 2010 to 2024). Inflammation of the peritoneum (tissue that lines the abdominal wall and covers most of the organs in the abdomen). "Overall, these data establish a new link between how much DNA a particular antibiotic causes bacteria to release, subsequent TLR9-driven macrophage inflammation (or lack thereof), and survival outcomes in a murine peritonitis model." (PMID 39609397, 2024). "To understand the roles of TLR9 in these FRC subsets during peritonitis, we challenged the mice with ODN (a TLR9 agonist, 2.5 nmol/mouse, i.p.), LPS (a TLR4 agonist, 5mg/kg, i.p.), and CLP for 18 hours." (PMID 38827745, 2024). "Notably, we found that adoptive transfer of Tlr9-/–CD55lo FRC from mesenteric FALC more effectively improved the survival during peritonitis compared with WT-FRC or Tlr9-/–CD55hi FRC." (PMID 38827745, 2024). "Notably, we found that adoptive transfer of Tlr9-/- -Cd55lo- FRC derived from mesenteric FALC improved the therapeutic efficacy in CLP-induced peritonitis." (PMID 38827745, 2024). "TLR4 and TLR9 are major receptors sensing pathogen-associated molecular patterns (PAMP) and damage-associated molecular patterns (DAMP) to regulate peritoneal immunity during CLP-induced peritonitis." (PMID 38827745, 2024). "Therefore, inhibition of TLR9 in the CD55lo FRCs from adipose tissue could be a useful strategy to improve the therapeutic efficacy of FRC-based therapy for peritonitis." (PMID 38827745, 2024).
Salmonella Infections (5 papers, 2010 to 2024). Infections with bacteria of the genus SALMONELLA. "Similarly, deficiency in Tlr9 and the processing molecule Unc93B1 significantly reduced the epithelial cell response to Salmonella infection." (PMID 25210785, 2014). "TLR9 is vital for resistance to Salmonella infection, and its absence leads to severe Salmonella hepatitis, a high bacterial load, sustained inflammation and tissue damage." (PMID 39456517, 2024). "TLR4 and TLR21 (which is functionally equivalent to mammalian TLR9) recognize and bind with their respective ligands LPS and Unmethylated (or 5′—C—phosphate—G—3′) DNA sequences are considered to be key players in immunity against Salmonella infection." (PMID 34446765, 2021). "Also in the case of Salmonella infection along with the CpG treatment there was a significant increase in the TLR-9 level." (PMID 21048937, 2010). "TLR9 mRNA expression was comparable in GF and BB12 groups but was downregulated by Salmonella infection." (PMID 36768650, 2023). "To determine the effect of Salmonella infection or the CpG ligand treatment on TLR-9 expression, we performed western blot to determine the protein level of TLR-9 in DCs." (PMID 21048937, 2010). "In accordance with previous reports; we also observed that Salmonella infection does not significantly increase the TLR-9 level in the infected DCs compared to the control cells." (PMID 21048937, 2010). "The antagonist treatment does not significantly increase the bacterial load even at 2 or 12 h of growth indicating Salmonella infection does not itself activate TLR-9 signaling." (PMID 21048937, 2010). "Interestingly, in the same study it was observed that live Salmonella infection did not increase TLR-9 expression as the bacterial DNA might not have been accessible to the TLR-9 receptor." (PMID 21048937, 2010).
sarcoidosis (5 papers, 2006 to 2020). Sarcoidosis is a multisystemic disorder of unknown cause characterized by the formation of immune granulomas in involved organs. "A case-control study was done to determine possible genetic and functional differences in TLR-9 between patients with sarcoidosis and healthy controls." (PMID 33173621, 2020). "Another study found a significant association between TLR9 expression and CD4+ lymphocytes in BAL of patients with sarcoidosis." (PMID 31182092, 2019). "Increased TLR9 expression in alveolar macrophages derived from patients with sarcoidosis was also reported and these cells secreted higher levels of cytokines in response to in vitro stimulation." (PMID 31182092, 2019). "TLR-9 mRNA expression was marginally increased in patients with sarcoidosis when compared to healthy subjects (mean ± SD, 213.52 ± 211.95 versus 0.58 ± 0.53; P = 0.05)." (PMID 20937083, 2010). "Additionally, in assessing the functional aspect of TLR-9, patients with sarcoidosis produced significantly less interferon-gamma upon stimulation with different stimuli." (PMID 33173621, 2020).
Stroke (5 papers, 2014 to 2023). Sudden impairment of blood flow to a part of the brain due to occlusion or rupture of an artery to the brain. "CpG binds to Toll-like receptor 9 (TLR9) causing initialization of an inflammatory response that limits visible ischemic damages upon subsequent stroke." (PMID 33078250, 2021). "In the context of an experimental pre-conditioning event, systemic application of LPS, Pam3CysSK4, or CpG ODN, activating TLR4, TLR2, and TLR9, respectively, prior to an experimental stroke results in protection of the mouse brain." (PMID 25239168, 2014). "Similarly, in a mouse stroke model, TLR3 and TLR9 did not confer protection to neural cells during middle cerebral artery occlusion." (PMID 30809253, 2018).
acute pancreatitis (4 papers, 2016 to 2020). An acute inflammatory process that leads to necrosis of the pancreatic parenchyma. "We demonstrated that the TLR9 and NF-κB pathway is activated in acute pancreatitis and increases the inflammatory process." (PMID 32076577, 2020). "In patients with acute pancreatitis, the serum TLR9 and NF-κB values were significantly higher than those of the control group [1104.44 ± 339.20 vs. 702.08 ± 203.94; p < 0.001 and 8.04 ± 1.76 vs. 4.76 ± 1.13; p < 0.001, respectively]." (PMID 32076577, 2020). "In this study, we tested the predictive value of TLR9 and NF-κB for the diagnosis and prognostification of acute pancreatitis, where we compared the TLR9 and NF-κB among the patient and control groups." (PMID 32076577, 2020). "In our study, we demonstrated that the TLR9 and NF-κB pathway is activated in acute pancreatitis, which is an inflammatory process." (PMID 32076577, 2020). "The activated TLR9 pathway in acute pancreatitis also induces NF-κB, which activates the inflammation of the pancreas and the surrounding tissues." (PMID 32076577, 2020). "It is known that NF-κB and TLR9 induce inflammatory response and systemic reactions in acute pancreatitis." (PMID 32076577, 2020). "The TLR9 rate was upregulated in the acute pancreatitis rats during 3, 6, and 12 h groups when compared with the control group." (PMID 32076577, 2020). "ROC analyses demonstrated the performances of the TLR9 and NF-κB in the prediction of acute pancreatitis." (PMID 32076577, 2020). "Interestingly, TLR9 has been shown to act in close collaboration with NALP3 inflammasome for example in acetaminophen-induced hepatotoxicity and in acute pancreatitis." (PMID 27888633, 2016).
adenovirus infection (4 papers, 2010 to 2022). "Polyomavirus and adenovirus infections are also associated with glioma development, and adenovirus infection promotes GBM stem cell formation through the TLR9/NEAT1/STAT3 pathway." (PMID 36497459, 2022). "Adenovirus infection of both human and murine plasmacytoid dendritic cells resulted in Tlr9-MyD88-dependent type 1 interferon expression." (PMID 20419141, 2010). "In murine peritoneal macrophages and bone marrow derived macrophages, IL-6 expression upon adenovirus infection was mediated by Tlr9." (PMID 20419141, 2010). "Type 1 interferon expression upon adenovirus infection of plasmacytoid dendritic cells was dependent upon the Tlr9 pathway." (PMID 20419141, 2010). "Similarly, expression of IL-6 after intravenous administration of adenovirus or adenovirus infection of bone marrow macrophages was dependent on Tlr9 and Myd88, respectively." (PMID 20419141, 2010). "Innate immunity to adenovirus infections involves the TLR2 and TLR9 pathway, and emerging evidence indicates that the inflammasome participates in the antiviral response." (PMID 22928129, 2012). "Mice lacking the toll-like receptor 9 (Tlr9) molecule, which acts as a pathogen DNA-sensing molecule within the cell, developed clinical inflammation upon adenovirus infection similar to wild type mice." (PMID 20419141, 2010).
airway hyperresponsiveness (4 papers, 2011 to 2021). "In Tlr9–/– mice, airway hyperresponsiveness (AHR) and the number of eosinophils decreased, and production of the Th2 cytokines IL-13, IL-5, and IL-4 was suppressed, compared with in wild-type mice." (PMID 33093516, 2020). "TLR9 knockout mice have lower airways hyperresponsiveness in a model of fungal asthma." (PMID 21324137, 2011). "In models of RSV immunization, TLR9 agonists formulated with formalin-inactivated RSV have increased immunogenicity while ameliorating pulmonary pathology and reducing airway hyperresponsiveness normally exacerbated by FI-RSV immunization." (PMID 32849580, 2020). "It has been reported that IFN-γ production, induced through TLR9 activation, could alleviate ILC2-driven airway hyperresponsiveness (AHR) and airway inflammation." (PMID 34970267, 2021).
Anxiety (4 papers, 2016 to 2025). Intense feelings of nervousness, tension, or panic often arise in response to interpersonal stresses. "Failure of the innate immune system to properly engage TLR9 is associated with anxiety-related inflammation, and peripheral administration of specific TLR9 oligonucleotide activators has been shown to prevent post-traumatic inflammation and anxiety in stressed mice." (PMID 40558558, 2025). "Interruption of this stress-provoked pro-inflammatory NF-κB pathway by toll-like receptor 9 (TLR9) activation reduced the elevated IL-1 levels and tempered the anxiety levels in the predator-stressed mice." (PMID 27375619, 2016).
atopic dermatitis (4 papers, 2012 to 2017). "In addition to producing elevated levels of cathelicidin, keratinocytes in psoriatic LS skin have been found to express significantly higher levels of TLR9 mRNA in comparison to NL psoriatic skin or that of atopic dermatitis." (PMID 24386404, 2013).